GJA5 (gap junction protein alpha 5)
Description:
One gap junction consists of a cluster of closely packed pairs of transmembrane channels, the connexons, through which materials of low MW diffuse from one cell to a neighboring cell.
Synonyms: Cx40; ATFB11
Tractability: Antibody: its Gene Ontology location is reachable by antibodies, with high confidence; UniProt places it where antibodies can reach, with medium confidence; UniProt predicts a signal peptide or a membrane-spanning region.
Gene: Protein-coding gene on chromosome 1 (147,756,199 to 147,773,362, reverse strand). Ensembl gene ENSG00000265107.
Subcellular location: Cell membrane; Cell junction, gap junction
Pathways (Reactome):
Vesicle-mediated transport: Gap junction assembly
Gene Ontology:
Molecular function: gap junction channel activity involved in atrial cardiac muscle cell-AV node cell electrical coupling; gap junction channel activity involved in AV node cell-bundle of His cell electrical coupling; gap junction channel activity involved in bundle of His cell-Purkinje myocyte electrical coupling; gap junction channel activity involved in cardiac conduction electrical coupling; gap junction hemi-channel activity; protein binding; gap junction channel activity involved in Purkinje myocyte-ventricular cardiac muscle cell electrical coupling; gap junction channel activity involved in SA node cell-atrial cardiac muscle cell electrical coupling; connexin binding; disordered domain specific binding; gap junction channel activity
Biological process: angiogenesis; atrial cardiac muscle cell to AV node cell communication by electrical coupling; atrial septum development; AV node cell to bundle of His cell communication by electrical coupling; bundle of His cell to Purkinje myocyte communication by electrical coupling; cell communication by electrical coupling involved in cardiac conduction; gap junction assembly; mitral valve development; outflow tract morphogenesis; pulmonary valve formation; regulation of atrial cardiac muscle cell action potential; regulation of atrial cardiac muscle cell membrane depolarization; regulation of AV node cell action potential; regulation of bundle of His cell action potential; regulation of cardiac muscle contraction; regulation of Purkinje myocyte action potential; ventricular septum development; artery morphogenesis; cardiac conduction system development; cell-cell signaling; heart development; Purkinje myocyte to ventricular cardiac muscle cell communication by electrical coupling; regulation of ventricular cardiac muscle cell membrane depolarization; regulation of ventricular cardiac muscle cell membrane repolarization; SA node cell to atrial cardiac muscle cell communication by electrical coupling; and 13 more
Cellular component: connexin complex; gap junction; intercalated disc; plasma membrane
Genetic constraint (gnomAD): Loss-of-function variants: 5 observed, 13.75 expected, observed/expected ratio (o/e) 0.36, 90% interval 0.19 to 0.76. The upper end of that interval is the gene's LOEUF score, 0.76, which puts it in group 3 of 6, group 1 being the genes least tolerant of losing a copy. Missense variants: 390 observed, 484.09 expected, observed/expected ratio (o/e) 0.81, 90% interval 0.74 to 0.88. Synonymous variants: 193 observed, 191.84 expected, observed/expected ratio (o/e) 1.01, 90% interval 0.89 to 1.13.
Gene-disease validity (ClinGen):
ClinGen rates the evidence that GJA5 causes each of these diseases.
congenital heart disease (autosomal dominant): Disputed. A heart disease that is present at birth.
Homologues: Orthologues: chimpanzee GJA5 (99% identical), macaque GJA5 (97% identical), dog GJA5 (91% identical), pig GJA5 (89% identical), rabbit GJA5 (84% identical), guinea pig GJA5 (84% identical), mouse Gja5 (83% identical), rat Gja5 (82% identical), tropical clawed frog gja5 (69% identical), zebrafish gja5a (58% identical), zebrafish gja5b (57% identical). Paralogues in human: GJA8 (49% identical), GJA3 (46% identical), GJA10 (40% identical), GJA4 (39% identical), GJA1 (39% identical), GJA9 (39% identical), GJC1 (32% identical), GJC2 (32% identical), GJB1 (29% identical), GJB6 (29% identical), GJD2 (29% identical), GJB2 (28% identical), and 8 more.
Diseases named in the same sentence as GJA5 in open-access papers:
GJA5 is named in the same sentence as 118 diseases in open-access papers, as found by Europe PMC text mining. Sharing a sentence is not in itself a finding about the gene and the disease. The quoted sentences say what the papers report.
atrial fibrillation (44 papers, 2012 to 2025). A disorder characterized by an electrocardiographic finding of a supraventricular arrhythmia characterized by the replacement of consistent P waves by rapid oscillations or fibrillatory waves that vary in size, shape and timing and are accompanied by an irregular ventricular response. "Atrial fibrillation (AF)-linked GJA5 (Cx40) variants showed the lowest number of variants among these α connexins." (PMID 34360596, 2021). "In contrast, deleterious mutations in human GJA5 are associated with atrial fibrillation and mutant Gja5 mice show atrial arrhythmias and altered conduction velocity." (PMID 34607956, 2021). "Somatic mutations in GJA5 have been linked to atrial fibrillation and Gja5-knockout mice exhibit conduction defects and a higher predisposition to atrial arrhythmias." (PMID 33497365, 2021). "As cardiac myocytes are also rich in gap junctions for coordinating electrical activity, it is not surprising that germline heterozygous missense mutations in GJA5 (Cx40; e.g., phenylalanine for isoleucine, I75F) also underlie lone atrial fibrillation." (PMID 30893836, 2019). "While several heterozygous GJA5 mutations were identified in patients suffering from atrial fibrillation, transgenic mice carrying one of these mutations, Cx40A96S, developed hypertension only when both alleles were mutant." (PMID 27871290, 2016). "GJA5 codes for the gap junction connexin-40 (Cx40), molecule responsible for electrical impulse conduction in the heart and is associated with atrial fibrillation." (PMID 26086673, 2015). "A germline mutation in the GJA5 gene, which encodes Cx40, resulting in a truncated Cx40 (Q49X) was identified in a large Chinese family with lone (idiopathic) atrial fibrillation (AF)." (PMID 24626989, 2014). "The role of the impaired expression of GJA5 in sodium channel dysfunction remains unclear, despite the reported association of GJA5 mutations with atrial fibrillation." (PMID 35935653, 2022). "Several mutations as well as a rare polymorphism have been reported in the Cx40 GJA5 gene in human atrial fibrillation (AF) patients, but little or nothing is known about their functional impact on Cx40-based HCs." (PMID 36919695, 2023). "Several recent studies indicate somatic and germline mutations in the Cx40 gene (GJA5) are associated with lone atrial fibrillation (AF)." (PMID 24733048, 2014). "At the RNA level, RT-qPCR confirmed expression changes in CACNG4 (cardiac arrythmia), GJA5 (atrial fibrillation), THBS2 (angiogenesis inhibitor), ADD2 (membrane skeletal protein, synaptic plasticity), and HAND2 (neurogenesis)." (PMID 39508990, 2025). "Early onset atrial fibrillation (AF) linked variants were found in GJA5 (13 currently known), which encode a connexin, Cx40, abundantly expressed in several tissues including the atria of the heart." (PMID 34360596, 2021). "Transcripts of additional atrial fibrillation associated genes, such as those encoding the gap junction proteins GJA1 and GJA5, and the transcription factor, GATA541, and signaling pathways were also differentially expressed in the LA and RA." (PMID 30224797, 2018). "Human mutations in the gene encoding Cx40, GJA5, have been reported to cause atrial fibrillation, and the deletion of Cx40 in murine models results in myocardial hypertrophy, fibrosis, arrhythmia, and conduction disturbances (i.e. increased P-wave and QRS duration)." (PMID 30745457, 2019).
Hypertension (25 papers, 2012 to 2025). The presence of chronic increased pressure in the systemic arterial system. "Several studies also found that heterozygous mutations and deletions in GJA5 have been identified in patients with structural cardiac defects (especially aortic arch anomalies and tetralogy of Fallot) and essential hypertension." (PMID 39268082, 2024).
Arrhythmia (18 papers, 2008 to 2025). Any cardiac rhythm other than the normal sinus rhythm. "Cardiac gap junction connexins Cx40 (GJA5) and Cx43 (GJA1) have been implicated to have a role in developing arrhythmia and cardiac anomalies, including ToF." (PMID 41472692, 2025). "Another example is the ncRNA RP11-433J22.2 which was found for Cardiac Arrhythmia and is co-expressed with two gap junction genes (GJA4 and GJA5)." (PMID 37491351, 2023). "Four proteins (GJA1, TPM2, GJA5 and C1QBP) were related with cardiac arrhythmias, cardiac dysfunction and cardiac cell damage, and might also be responsible for DCM." (PMID 23940716, 2013).
Tetralogy of Fallot (5 papers, 2009 to 2024). A congenital cardiac malformation comprising pulmonary stenosis, overriding aorta, ventricular septum defect, and right ventricular hypertrophy. "Recently, GJA5 gene has been demonstrated to be a susceptibility gene for non-syndromic tetralogy of Fallot in humans." (PMID 27990414, 2016). "Enrichment of small genomic duplications spanning the GJA5 gene in cohorts with tetralogy of Fallot and cardiac abnormalities in mice with a targeted GJA5 deletion imply that dosage variations of GJA5 contribute to CHD." (PMID 39240962, 2024).
atrial standstill (4 papers, 2013 to 2024). Atrial standstill is a rare cardiac rhythm disease with a few familial and sporadic cases described to date that is characterized by a transient or permanent absence of electrical and mechanical atrial activity. "As a critical candidate gene for the cardiac phenotype, GJA5 encodes the gap junction protein connexin 40 (CX40), and its heterozygous mutations would lead to familial atrial fibrillation 11 (OMIM 614049) and atrial standstill (OMIM 108770)." (PMID 37692779, 2023). "Among them, GJA5 (OMIM * 121013) encodes gap junction protein, a5, and heterozygous pathogenic variants in GJA5 is associated with familial atrial fibrillation 11 (OMIM # 614049) and atrial standstill (OMIM # 108770)." (PMID 39268082, 2024).
congenital heart disease (4 papers, 2009 to 2023). "The authors screened by real-time quantitative PCR a total of 505 unrelated congenital heart disease cases for deletions or duplications of Cx40 gene (GJA5) and identified three cases with a 1.5 to 3-Mb deletion of this region; however the microdeletion was also present in some unaffected parents." (PMID 20030804, 2009).
schizophrenia (4 papers, 2009 to 2025). A major psychotic disorder characterized by abnormalities in the perception or expression of reality. "Importantly, GJA5 and GJA8 are considered candidate genes for schizophrenia, largely due to their involvement in neural signaling and their location within the 1q21 chromosomal region, which is consistently linked to the disorder." (PMID 40792073, 2025).
squamous cell carcinoma (3 papers, 2017 to 2023). A carcinoma arising from squamous epithelial cells. "New ultraviolet target genes, including GJA5, have been identified, and they are often dysregulated in human squamous cell carcinoma." (PMID 33425993, 2020). "Our analysis also identified several new UV target genes, including CYP24A1, GJA5, SLAMF7 and ETV1, which were frequently dysregulated in human squamous cell carcinomas, highlighting their potential as new molecular targets for prevention or treatment of UVR-induced skin cancers." (PMID 28211524, 2017).
hepatocellular carcinoma (2 papers, 2023 to 2024). A malignant tumor that arises from hepatocytes. "GJA5 was identified as one of OS related genes for hepatocellular carcinoma patients, who received transarterial chemoembolization treatment." (PMID 38039294, 2023).
Holt-Oram syndrome (2 papers, 2023 to 2024). Holt-Oram syndrome (HOS) is the most common form of heart-hand syndrome and is characterized by skeletal abnormalities of the upper limbs and mild-to-severe congenital cardiac defects. "Mechanistic work revealed that Tbx5 and Nk2.5 synergistically interact to promote the expression of the gap junction protein Cx40 (Gja5), reduction of which is assumed to contribute to the cardiac anomalies in Holt-Oram syndrome." (PMID 37125615, 2023). "Holt-Oram syndrome is partially caused by variants in the TBX5 gene, and GWAS studies on AF have shown several significant loci with nearest genes known to be important for heart development and causal for CHD, such as NKX2-5, GATA4, GJA1, and GJA5." (PMID 38454350, 2024).
osteosarcoma (2 papers, 2023 to 2024). A usually aggressive malignant bone-forming mesenchymal neoplasm, predominantly affecting adolescents and young adults. "A risk model composing of ZYX, GJA5, GAL, GRAMD1B, and CKMT2 was established for assessing osteosarcoma prognosis." (PMID 38039294, 2023). "Considering the heterogeneity between molecular subtypes defined by specific oxidative stress genes, we identified the DEGs between the two molecular subtypes and deduced a risk assessment system composing of ZYX, GJA5, GAL, GRAMD1B, and CKMT2 for the prognosis of osteosarcoma." (PMID 38039294, 2023).
ventricular fibrillation (2 papers, 2024 to 2025). A disorder characterized by an electrocardiographic finding of a rapid grossly irregular ventricular rhythm with marked variability in QRS cycle length, morphology, and amplitude. "Mutations and loss of function of the GJA5 gene are closely related to the occurrence of isolated ventricular fibrillation in humans." (PMID 38454924, 2024).
cardiovascular malformations (1 paper, 2022). "In the cardiovascular malformations associated with 16p11.2 microdeletion syndrome, our research found that 32% (8/25) of microdeletion regions of cardiovascular malformations contain TBX1, GJA5, HIRIP3, and other genes." (PMID 36553582, 2022).
dyslexia (1 paper, 2021). A learning disorder characterized by an impairment in processing written words. "Nonetheless, active analyses of the genotype–phenotype association have revealed some possible linkages; for example, GJA5 and cardiac phenotypes, neurexins/neuroligins and synaptic differentiation, or ROBO1 and dyslexia." (PMID 34071723, 2021).
glomerular disease (1 paper, 2024). "Even if the role of GJA5, TNS1, and CCND1 in glomerular disease requires further investigation (beyond the scope of this work), they might represent a biomarker signature of progressive glomerular damage, independent of the etiology." (PMID 38516889, 2024).
idiopathic ventricular fibrillation (1 paper, 2017). "Screening of patients with idiopathic ventricular fibrillation identified two missense mutations in IRX3, both of which had reduced ability to increase Gja5/Cx40 or Scn5a expression in heterologous expression systems." (PMID 29098150, 2017).
skin cancer (1 paper, 2017). "We found multiple UV target genes to be critical to the survival of skin cancer cells, including CD200, GJA5, GPR115, KLK7, SLAMF7 and SLP1." (PMID 28211524, 2017).
sudden cardiac death (1 paper, 2021). "For example, a literature review evaluated and summarized the effect of 53 SNPs on sudden cardiac death (SCD) and found that rs6684209, rs3814843, and rs35594137 in CASQ2, CALM1, and GJA5, respectively, had the most significant association with SCD." (PMID 34912794, 2021).
tumor (21 papers, 2013 to 2024). "The exact role of GJA5 in tumor development is unknown, but it can facilitate the connection of blood vessel wall cells and is a constitutive vascular gap junction protein, suggesting a potential link to vascular permeability." (PMID 38586328, 2024). "The findings demonstrated that both GJA5 and GJB1 exhibited decreased expression in tumor tissues and elevated expression in normal tissues (p< 0.001)." (PMID 38454924, 2024). "Employing the TS dataset, a comprehensive analysis was conducted to examine the differences in gene expression between GJA5 and GJB1 in tumor tissues and normal tissues." (PMID 38454924, 2024). "Given the results of the differential expression analysis, we speculated that GJA5 and GJB1 act as tumor suppressors in ccRCC." (PMID 38454924, 2024).
cancer (10 papers, 2016 to 2025). A tumor composed of atypical neoplastic, often pleomorphic cells that invade other tissues. "The Pan-cancer analysis revealed that GJA5 exhibited the highest expression level in ccRCC, whereas GJB1 was the 12th highest in terms of expression in ccRCC." (PMID 38454924, 2024).
cardiac disease (3 papers, 2022 to 2024). "In addition to GJA1 and GJA5, one mutation (p.Arg75His) in the GJC1 (encoding Cx45) gene has been reported to be related to heart disease to date." (PMID 35457072, 2022).
adenocarcinoma (1 paper, 2009). A common cancer characterized by the presence of malignant glandular cells. "Besides significant regulation of tight junction coding genes we found the gap junction protein Gja5 (gap junction membrane channel protein alpha 5 or so called connexin 40) −7.3-fold down regulated in adenocarcinoma and −8.7-fold repressed when compared to non-transgenic cells." (PMID 19812696, 2009).
GJA5 also shares sentences with these, for which no sentence is quoted: atherosclerosis (14 papers); diabetes (8); cardiomyopathy (6); heart failure (5); ischemia (5); cardiac arrhythmia (4); cardiac hypertrophy (4); pulmonary hypertension (4); Ventricular arrhythmia (4); Atrial Familial Fibrillation (3); depression (3); endothelial dysfunction (3); Myocardial fibrosis (3); Sepsis (3); ventricular septal defect (3); acute myocarditis (2); atrioventricular block (2); breast carcinoma (2); cardiovascular diseases (2); congestive heart failure (2); dilated cardiomyopathy (2); essential hypertension (2); fibrosis (2); glioma (2); Hypercholesterolaemia (2); idiopathic pulmonary fibrosis (2); maturity onset diabetes (2); melanoma (2); obstructive sleep apnea (2); paroxysmal AF (2).
A further 66 diseases each share a sentence with GJA5 in 2 papers or fewer.